SPG21 (SPG21 abhydrolase domain containing, maspardin)
Description:
May play a role as a negative regulatory factor in CD4-dependent T-cell activation.
Synonyms: ACP33; BM-019; GL010; MAST; ABHD21
Tractability: Antibody: UniProt places it where antibodies can reach, with high confidence. PROTAC: ubiquitination databases record sites on it; its protein half-life has been measured.
Gene: Protein-coding gene on chromosome 15 (64,963,022 to 64,990,312, reverse strand). Ensembl gene ENSG00000090487.
Subcellular location: Cytoplasm, cytosol; Membrane; Endosome membrane; Golgi apparatus, trans-Golgi network membrane
Subcellular location (Human Protein Atlas): Cytosol; Vesicles
Gene Ontology:
Molecular function: CD4 receptor binding; protein binding
Biological process: antigen receptor-mediated signaling pathway; cell surface receptor signaling pathway
Cellular component: cytosol; trans-Golgi network transport vesicle; endosome membrane; Golgi apparatus; membrane
Genetic constraint (gnomAD): Loss-of-function variants: 18 observed, 29.95 expected, observed/expected ratio (o/e) 0.6, 90% interval 0.41 to 0.89. The upper end of that interval is the gene's LOEUF score, 0.89, which puts it in group 3 of 6, group 1 being the genes least tolerant of losing a copy. Missense variants: 280 observed, 334.7 expected, observed/expected ratio (o/e) 0.84, 90% interval 0.76 to 0.92. Synonymous variants: 122 observed, 117.28 expected, observed/expected ratio (o/e) 1.04, 90% interval 0.9 to 1.21.
Homologues: Orthologues: chimpanzee SPG21 (100% identical), dog SPG21 (99% identical), guinea pig SPG21 (98% identical), rabbit SPG21 (98% identical), mouse Spg21 (98% identical), macaque SPG21 (94% identical), pig SPG21 (94% identical), rat Spg21 (91% identical), tropical clawed frog spg21 (90% identical), zebrafish spg21 (88% identical).
Diseases named in the same sentence as SPG21 in open-access papers:
SPG21 is named in the same sentence as 12 diseases in open-access papers, as found by Europe PMC text mining. Sharing a sentence is not in itself a finding about the gene and the disease. The quoted sentences say what the papers report.
mast syndrome (4 papers, 2012 to 2021). "Mast syndrome is caused by bi-allelic mutations in the ACP33 (SPG21; HSP-ACP33) gene, coding for a protein called maspardin." (PMID 35111129, 2021). "This is the first report of Chinese patient with Mast syndrome carrying a large homozygous SPG21 deletion." (PMID 34492745, 2021). "Network 24 contained also several genes previously associated with neurological diseases, like ZFYVE27 (hereditary spastic paraplegia), ATB1B1 (neurodegeneration of photoreceptors) and SPG21 (Mast syndrome)." (PMID 23028713, 2012).
Ataxia (2 papers, 2023 to 2026). Ataxia refers to impaired coordination of voluntary muscle movement. "It has been known for >20 years that mutations in the SPG21 gene, which encodes maspardin, cause progressive SPG accompanied by cognitive impairment and ataxia." (PMID 41400694, 2026). "For instance, all patients with SPG10 and SPG21 presented with spasticity (100%) and gait disturbance (100%); all SPG26 cases manifested initially with ataxia (100%)." (PMID 36441344, 2023).
hereditary spastic paraplegia (2 papers, 2012 to 2026). Hereditary spastic paraplegias (HSP) comprise a genetically and clinically heterogeneous group of neurodegenerative disorders characterized by progressive spasticity and hyperreflexia of the lower limbs. "Mutations in the SPG21 gene underlie hereditary spastic paraplegia (SPG) type 21 (also known as Mast syndrome)." (PMID 41400694, 2026).
cavernous cerebral malformation (1 paper, 2017). "SPG21 is a negative pro-inflammatory CD4+ cells regulator that can lead to spastic paraplegia while the aberrant PDCD10 expression can be associated with the development of cavernous cerebral malformation." (PMID 28423529, 2017).
Chorea (1 paper, 2023). Chorea (Greek for 'dance') refers to widespread arrhythmic involuntary movements of a forcible, jerky and restless fashion. "Majority of HSP cases manifested with chorea had SPG21 genotype (60%)." (PMID 36441344, 2023).
Dystonia (1 paper, 2016). An abnormally increased muscular tone that causes fixed abnormal postures. "As complicated HSP could encompass the parapyramidal signs (including dystonia), for example in SPG21,SPG35,SPG56, so we take the next-gene sequencing on HSP." (PMID 27835968, 2016).
neurological diseases (2 papers, 2012 to 2025). "Hereditary spastic paraplegia type 21 (SPG21) is an inherited neurological disorder caused by biallelic mutations in the SPG21 gene, which encodes a protein named SPG21 or maspardin." (PMID 40833810, 2025).
SPG21 also shares sentences with these, for which no sentence is quoted: paraplegia (3 papers); Cognitive impairment (1); developmental delay (1); mental disorder (1); Tremor (1).